EZH2 (enhancer of zeste 2 polycomb repressive complex 2 subunit)
Diseases named in the same sentence as EZH2 in open-access papers (continued):
Sharing a sentence is not in itself a finding about the gene and the disease.
tumor (continued). "Some studies have shown that epigenetic inhibitors, such as BET, LSD1 and EZH2 inhibitors, are already used in combination with anti-PD1 therapy activating the antitumor immune response by increasing the persistence of T cells in the tumor microenvironment." (PMID 36233212, 2022). "As expected, TAM induction of Ezh2 deletion depleted MYCN, significantly inhibited expression of representative MYCN metabolic targets and uptake of the radiotracer 18F-deoxyglucose (FDG) to tumor sites, and dramatically prolonged the survival of TH-MYCN mice." (PMID 35013218, 2022). "Additionally, we performed immunohistochemical staining of EZH2, EED, SUZ12, and H3K27me3 on archived UTUC tumor tissues to reveal the presence of PRC2." (PMID 36428492, 2022). "Moreover, HER2-targeted therapies combined with EZH2 inhibitors in anti-HER2 resistant cell lines and mouse models engrafted with trastuzumab-resistant cells showed significant tumor growth arrest in both cases." (PMID 35800378, 2022). "In turn, the change in the concentration of EZH2 targets (non-protein neuroectodermal marker GD2) allows chimeric antigen receptor gene-modified T cell therapy to be applied to the tumor." (PMID 35454895, 2022). "In HCC, overexpression of EZH2 represses miR-622 through H3K27me3 deposition and results in CXCR4 upregulation and unfavorable prognosis, while BMI1 enhances TGFβ2/SMAD pathway and facilitates tumor cell proliferation and cell cycle progression." (PMID 36566204, 2022). "In addition, tumor sphere-forming assay showed that LINC01419 silencing expression significantly inhibited LUAD cell sphere-forming, EZH2 silencing expression inhibited LUAD cell sphere-forming." (PMID 36050791, 2022). "EZH2 functions as the catalytic subunit of the polycomb repressive complex 2 (PRC2), which trimethylates lysine 27 on histone 3 (H3K27me3), resulting in transcriptional silencing of numerous genes, including tumor suppressors." (PMID 35852858, 2022). "Moreover, suppressing EZH2 activity by GSK126 increased myeloid-derived suppressor cells (MDSCs) and consequent suppression of anti-tumor immunity." (PMID 35432300, 2022). "Moreover, downregulation of EZH2 or BRCA1 sensitized A2780/DDP cells to cisplatin, which contradicts BRCA1’s tumor-suppressing role but is in line with the concept that its upregulation is associated with DNA repair-mediated resistance to cisplatin." (PMID 36230683, 2022). "The results revealed that tumor volume and weight were much smaller with sh-EZH2 treatment in comparison with control mice under CDDP treatment, while this effect was abolished by AKT or EZH2 overexpression." (PMID 35184652, 2022). "We next treated RB1 non-mutated tumor cells with 10 μM GSK503 for 72 h and found that the binding of EZH2 to the RB1 promoter was abolished, which led to a decrease in H3K27me3 in the RB1 promoter." (PMID 36175480, 2022). "We performed RNA-seq of EZH2 WT and EZH2 GOF (n = 3 and n = 4 respectively) tumor samples." (PMID 35395831, 2022). "Inhibition of PRC2 core factor EZH2 by a specific inhibitor was able to restore TET1 expression and suppress TNBC cell propagation, providing us with a novel strategy for TET1 induction and tumor suppression." (PMID 35805009, 2022). "EZH2, TUBG1, and PPM1G are related to the ferroptosis gene, FANCD2, and may be involved in tumor biological behaviors mediated by ferroptosis." (PMID 36686830, 2022). "Surprisingly, the combination of EZH2-92aa inhibition, NK cell injection, and the anti-PD1 antibody fully maximized survival and even cleared the tumour masses in two mice from the treated group, showing a better effect than the combined treatment with EZH2-92aa inhibition plus NK cells." (PMID 35970825, 2022). "As EZH2 is a methyltransferase, EZH2 and USP7 may regulate the levels of methylation and ubiquitination of cGAS, which leads to the production of inflammatory factors in tumor cells after the activation of cGAS." (PMID 35163710, 2022).
tumor (continued). "Owing to the competitive binding of EPIC to the secondary structure within lncRNA HOTAIR that is recognized by EZH2, we successfully blocked the PRC2 recruitment and remodeled the trimethylation level of H3K27 to prompt the expression of tumor suppressor genes." (PMID 36276638, 2022). "Furthermore, the enhancer of zeste homolog 2 (EZH2) has been identified as a functional target of miR-506-3p, which is closely related to the potential for tumor metastasis 25-27." (PMID 35154460, 2022). "Inactivation of EZH2 or DNMT1 exerts much immunological relevance, which may affect its anti-tumor therapeutic efficacy while enabling immune-modifying agents." (PMID 36038549, 2022). "EZH2 in CAFs can participates the peritoneal tumor formation of GC by demethylating H3K27me3 markers; On the other hand, CAFs-derived VEGF promoting the proliferation and angiogenesis of human umbilical vein endothelial cells via regulating EZH2/VASH1 pathway." (PMID 36401232, 2022). "A study found that EZH2-mediated H3K27me3 along with DNMT1-mediated DNA methylation inhibited generation of Th1 chemokines, including CXCL9 and CXCL10, which helped effector T cells migrate to microenvironment in tumor." (PMID 36545327, 2022). "EZH2, a subunit of PRC2, shows context-dependent oncogenic and tumor suppressor functions." (PMID 35597793, 2022). "EZH2, a subunit of the PRC2 epigenetic regulator, is involved in tumor progression." (PMID 36000567, 2022). "Another study reported that EZH2 was negatively correlated with the IFN-gamma signaling pathway and positively correlated with the MYC and glycolytic signaling pathways, with respect to tumor growth and aggressiveness." (PMID 36275676, 2022). "DZNep treatment can markedly suppress H3K27 methylation (rather than H3K9 methylation) in diverse tumor cells (such as MB-468 BC cells) by depleting PRC2 component levels in cells (EZH2, SUZ12, and EED))." (PMID 36188615, 2022). "No significant reduction in EZH2-positive cells was observed in TMZ-treated tumor tissue compared to the matched control or when comparing the expression of EZH2-positive cells between the treated groups (p > 0.05)." (PMID 35216113, 2022). "Once EZH2 is amplified in cancer cells, TGFB1-mediated gene expression might be more vulnerable to activation and further facilitate tumor progression." (PMID 35085106, 2022). "Surprisingly, however, we neither detected a reduced relative tumor weight nor prolonged survival in the absence of EZH2." (PMID 35884510, 2022). "In the 12Z-ESR1 model, in which ESR1 was stably overexpressed, we did not explore the regulation of ESR1 by EZH2, although EZH2 expression is negatively correlated with ESR1 expression in patient tumor tissues." (PMID 35326450, 2022). "The TMZ impact on PBT24 and SF8628 tumor PCNA expression was similarly significantly effective but did not alter EZH2 expression in the studied tumors." (PMID 35216113, 2022). "Therefore, the current research results suggest that EZH2, GRPEL2, NDRG1, and tumor size are reliable prognostic indicators." (PMID 36686830, 2022). "High EZH2 expression was significantly correlated with older age (p = 0.003), higher tumour grade (p < 0.001), negative IDH1 R132H immunoexpression (p = 0.039), a poor 5-year PFS (mean = 9.7 months, p < 0.001) and 5-year OS (mean = 28.2 months, p = 0.007)." (PMID 36292072, 2022). "BDNF-AS recruits EZH2 to down-regulate GSK-3β and silence the tumor-promoting gene GSK-3β." (PMID 35236381, 2022). "Further, EZH2 in combination with DNMT1 had a negative correlation with CD8+ T cells tumor infiltration and prognosis of OC patients." (PMID 36545327, 2022). "Preclinical studies have shown that inhibitors targeting DNA methyltransferases (DNMT), histone deacetylases (HDAC), enhancer of zeste homolog 2 (EZH2), bromodomain and extra-terminal domain (BET) proteins, and lysine-specific demethylase 1 (LSD-1), can improve anti-tumor efficacy of ICB." (PMID 36397155, 2022).
tumor (continued). "In vivo 7-day treatment of H3K27M DMG tumor bearing mice with an EZH2 inhibitor, Tazemetostat, did not alter proliferation or significantly impact survival." (PMID 35395831, 2022). "The expression levels of HDAC2 and EZH2 were significantly higher in multiple tumor types, indicating that HDAC2 and EZH2 may play important roles as oncogenes." (PMID 35892859, 2022). "Moreover, EZH2 and DNMT1 expression in tumor are negatively correlated with CD8+ T cells tumor-infiltration and patient outcomes." (PMID 36038549, 2022). "Genome-wide studies showed that EZH2 levels are negatively correlated with CD8+ T cells, mainly inhibiting the production of tumor TH1-type chemokines CXCL9 and CXCL10 and thus reducing the recruitment of T cells, while the binding of carboxyl structure of ARID1A to EZH2 can reverse this step." (PMID 36713412, 2022). "Further subanalysis of the exact tumor localization (pancreatic vs. intestinal vs. pulmonary NEN) revealed no site specific differences in OS or EZH2 expression." (PMID 35740494, 2022). "It is thought that these side effects are probably due to a lack of absolute tumor-related selectivity and consequential decrease of the basal expression of EZH2 in normal tissue." (PMID 36230683, 2022). "The involvement of G9a and EZH2 and their methylation dynamics in regulating the UPR pathway has only been explored in a tumor context, showing that inhibition of both HMTs promotes apoptosis and autophagy by preventing tumor progression." (PMID 35883846, 2022). "Since EZH2 impacts the expression of a variety of downstream target genes, it is not surprising that both the tumor promoting and tumor suppressive functions of EZH2 have been documented in the literature." (PMID 36230683, 2022). "Meanwhile, the activity of EZH2 in Treg cells maintains the stability of FOXP3 protein, increases the number of tumor-infiltrating FOXP3+ Tregs, alters the homeostatic balance with tumor effector T cells in the microenvironment and impairs the anti-tumor immune response." (PMID 36713412, 2022). "On the other hand, EZH2 or SUZ12 depletion cooperates with other oncogenes to accelerate myelodysplastic syndrome and Ras-driven transcription in peripheral nerve sheath tumors hinting at a tumor suppressive function of the PRC2 complex." (PMID 35395831, 2022). "Our finding of tumor cell enhanced antigen presentation machinery and antigen-specific CD8+ T cell cytotoxicity potentially may have overcome the dampening effect of Ezh2 inhibition on the function of CD8+ T cells." (PMID 33403469, 2021). "In addition, a network of EZH2 and its interacting proteins (UBC, CDK1, HDAC1, SUZ12, EED) was found to participate in miR-26a-mediated tumor progression." (PMID 34381816, 2021). "Together, these data suggest that simultaneously targeting of EZH2 and SQLE could significantly inhibit the tumour growth of HNSCC." (PMID 33986254, 2021). "In conclusion, miR-137 exerts tumor-suppressive functions in ESCC through forming a negative feedback loop with EZH2 and PXN." (PMID 33685449, 2021). "Among all these PRGs, AURKA and EZH2 drew our attention because these two genes were hub genes in the network sourced from IPA and were previously considered functional mostly in tumor progression." (PMID 35059393, 2021). "Immunohistochemical staining indicated that PDX tumours that did not respond to infigratinib highly and uniformly express EZH2, p-ErbB2, and/or p-ErbB3." (PMID 34156519, 2021). "To best understand the immune relevance of EZH2, we conducted correlation analysis of EZH2 in the tumour microenvironment and immune infiltration and generated a nomogram of pathways associated with EZH2 expression and prognosis." (PMID 33277782, 2021). "To validate this hypothesis, we first analyzed the protein levels of USP7, EZH2 and FOXO1 in human tissue arrays, including a series of paired tumor and adjacent normal tissue samples from the breast, kidney, lung, lymph node, ovary, esophagus and skin." (PMID 33849069, 2021).
tumor (continued). "Co-inhibition of EZH2 and DNMT1 in a tumour may have the potential to reprogram the immune microenvironment and increase the efficacy of PD-L1 checkpoint blockade therapy." (PMID 33669182, 2021). "Small clusters of cells that were positively stained for EZH2 were detected at the end of treatment cycle, while non-responders showed EZH2-positive cells in large sections of the tumour." (PMID 34156519, 2021). "Collectively, this study found that SPRY4 might act as an anti-tumor gene in CRC and SPRY4 exerted a suppressive effect on CRC progression via the inhibition of EZH2." (PMID 33879635, 2021). "Given the effectiveness of EZH2 in enhancing CSC dryness and motility, we hypothesized that EZH2 was delivered to tumor cells with enhanced malignant characteristics during UM liver metastasis." (PMID 34381816, 2021). "However, EZH2 and SMARCC1 antagonistically regulate several key tumor suppressors, such as the apoptosis‐promoting gene NOXA." (PMID 34213777, 2021). "We showed that the expression of both USP7 and EZH2 elevates during tumor progression, corresponding to a diminished FOXO1 expression, and the level of the expression of USP7 and EZH2 strongly correlates with histological grades and prognosis of tumor patients." (PMID 33849069, 2021). "Particularly, Treg cells in tumor tissues specifically express high levels of EZH2 and its histone modification H3K27me3 compared with those in non-lymphoid tissues, resulting in tumor tolerance." (PMID 33868269, 2021). "Consistently, the clinical correlation between the expression of EZH2, KLF-6, Sp-1, and SNHG6 in patient tumor samples also showed that both EZH2 and Sp-1 displayed the positive correlation with SNHG6, whereas KLF6 and p21 exhibited the negative correlation with SNHG6." (PMID 33431838, 2021). "Subsequently, through literature reviews about EGR1, JUN, and EZH2, we recognized that EGR1 and JUN could be tumor suppressors, whereas EZH2 can inhibit the expression of tumor suppressors." (PMID 34966410, 2021). "Hopefully, targeting EZH2 reprograms intratumoral Tregs; as for FL, namely, TFRs, which are more suppressive than Tregs in normal LNs, adoptive transfer of CAR-T cell therapy can be efficaciously executed even in the immunosuppressive tumor microenvironment." (PMID 34069564, 2021). "In addition, the EZH2 and H3K27me3 levels are increased only in Treg cells when compared to CD4+Foxp3- T cells in tumor tissues." (PMID 33868269, 2021). "Another point is that the study showing EZH2 inhibition promoted the expression of ISGs were performed in tumor cells with no exogenous IFN-I stimulation." (PMID 33868295, 2021). "In addition, treatment with a CUL-4A inhibitor or a proteasome inhibitor can substitute functionally for EZH2 inhibition both in increasing the steady-state level of DLC1 protein and in cooperating with the two kinase inhibitors for tumor treatment." (PMID 34862367, 2021). "In contrast, Mo-TAMs triggered a similar tumor cell proliferation rate in both DMSO and EPZ-6438-treated MCS, indicating that their tumor-promoting effects had abolished the antiproliferative activity of EZH2 inhibition." (PMID 33922336, 2021). "EZH2 inhibitors or CRISPR-mediated EZH2 depletion increased antigen presentation in the tumor cells, and increased antigen-specific CD8+ T-cell proliferation, IFNγ production and tumor cell cytotoxicity." (PMID 34680389, 2021). "Next, we selected several EZH2 or LSD1 potential targets (P15, P21, KLF2, PTEN, KLF2, LATS2, RND3, and NKD2) with tumor-suppressive role, and hypothesized that some of which might be associated with LINC00665-mediated carcinogenicity." (PMID 34094920, 2021).
tumor (continued). "We identified LINC02678 as a tumor promoter in NSCLC, which enhanced the growth and metastasis of NSCLC cells by binding with EZH2, indicating that LINC02678 may serve as a potential biomarker for cancer diagnosis and treatment." (PMID 34124072, 2021). "MiR-340 is a recently recognized tumor suppressor which targets and decreases expression of DNMT1, EZH2 and H3K27me3, leading to promoter hypomethylation and expression of E-cadherin as well as decreased expression of mesenchymal markers (N cadherin, vimentin and fibronectin) in TNBC cells." (PMID 33572395, 2021). "To explore whether blocking this adaptive mechanism by EZH2 inhibitor tazemetostat could reduce the development of chemotherapy resistance and maximize the therapeutic effect, we established a CAL51 tumor xenograft mouse model." (PMID 33823894, 2021). "Considering these findings, the lower EZH2 expression in platinum resistant HGSOC may result from more invasive cellular phenotypes and higher prevalence of stem-like tumor cells that contribute to an intrinsic resistance to chemotherapy." (PMID 34140011, 2021). "Furthermore, PRMT5, EZH2 and CDKN2B protein expression levels in CRC samples (80 tumor and 80 normal tissues) were analyzed by IHC staining." (PMID 33664859, 2021). "Immunohistochemical staining indicated that infigratinib-treated tumours of responders were largely negative for EZH2." (PMID 34156519, 2021). "Overexpression of EZH2 by the induction of trimethylation of H3K27 (H3K27me3) and the regulation of gene expression promoted self-renewal and dedifferentiation in oral cancer cells, ultimately leading to tumor progression and invasion." (PMID 34051847, 2021). "Additionally, EZH2 inhibitors reduced primary GBM cell viability when combined with TMZ and impaired GSC self‐renewal and tumor‐initiating capacity." (PMID 34586728, 2021). "In our study, we observed that Ili-A could reduce EZH2 protein and mRNA level and the expression of the downstream AURKA/PLK1 gene, which contribute to the anti-tumor effects against CRPC." (PMID 34776951, 2021). "EZH2 activity is high in RMS and other tumor tissues, particularly in metastatic cancer." (PMID 34372908, 2021). "Interestingly, the combination treatment exhibited a dramatic anti-tumor effect in EZH2 wild-type and mutant CDX and PDX xenograft models, demonstrating the potential synergistic anti-tumor effect of the two drugs in vivo." (PMID 34503063, 2021). "Similarly, overexpression of miR-3613-3p decreased tumor proliferation and migration in TNBC cells via targeting SMAD2 and EZH2, EZH2 like SMAD2/3, significantly promoting cancer cell proliferation in many cancer cells, including breast cancer." (PMID 33916931, 2021). "Furthermore, expression levels of UHRF1, EZH2, TTF2, WHSC1 and RAD54L transcripts correlated significantly with the tumor stages of NSCLC patients (P<0.05)." (PMID 33658396, 2021). "Similarly, a previous study revealed that EZH2 promotes breast CSC expansion and leads to tumor initiation." (PMID 33408782, 2021). "No clear correlation was observed between EZH2 expression in the tumor tissue and drug sensitivity; however, the sample number was relatively small." (PMID 34638497, 2021). "Pharmacologic inhibition of EZH2, CUL-4A, or the proteasome can increase the steady-state level of DLC1 protein, whose tumor suppressor activity is further increased by AKT and/or SRC kinase inhibitors, which reverse the direct phosphorylation of DLC1 by these kinases." (PMID 34862367, 2021). "We demonstrate that combined treatment with GSK126 and 5-Aza-2’-deoxycytidine to inhibit methyltransferase activity of EZH2 and DNMT3B synergistically block EC cell proliferation and EC tumor progression in both cell line-derived xenograft (CDX) and patient-derived xenograft (PDX) mouse models." (PMID 34175897, 2021).